SNORA11D (small nucleolar RNA, H/ACA box 11D)
Gene: Small nucleolar RNA gene on chromosome X (52,190,621 to 52,190,748, forward strand). Ensembl gene ENSG00000221475.
Gene Ontology:
Biological process: RNA processing
Cellular component: nucleolus
Homologues: Paralogues in human: SNORA11E (100% identical), SNORA11F (94% identical), SNORA11B (90% identical), SNORA11C (89% identical), SNORA11 (85% identical), SNORA11G (75% identical).